KDR (kinase insert domain receptor)
Diseases named in the same sentence as KDR in open-access papers (continued):
Sharing a sentence is not in itself a finding about the gene and the disease.
lung cancer (147 papers, 2006 to 2026). A malignant neoplasm involving the lung. "Mutations of KDR gene are observed in many cancers such as intestinal cancer, lung cancer, and skin cancer." (PMID 36746394, 2023). "KDR (also called VEGFR2) is a key modulator of angiogenesis and its overexpression is frequently associated with poorer prognoses in lung cancer patients." (PMID 32855362, 2020). "FLT1/VEGFR1 and KDR/VEGFR2 were also confirmed as direct targets of miR-200 in lung cancer cells, modulating invasion, metastasis, and radiosensitivity." (PMID 38766528, 2024). "Other frequently mutated genes in the tumor tissue samples used in our lung cancer study were FLT3 (altered in 87% of the samples), KDR (84%), CSF1R (72%), PIK3CA (59%), and ERBB4 (53%)." (PMID 35330454, 2022). "There is currently a small-molecule tyrosine kinase inhibitor (Moulder, #137) for KDR that is effective for lung cancer." (PMID 36160018, 2022). "Accordingly, KDR expression in cancer cells has been extensively observed in various human malignancies, including breast cancer, lung cancer, glioblastoma, gastrointestinal cancer, hepatocellular carcinoma, renal cell carcinoma, and ovarian cancer." (PMID 35313079, 2022). "Immunohistochemical studies showed lower expression levels of VEGFA and MMP-2 in lung cancer resections compared to pneumothorax and transplant biopsies, while in contrast TIMP-1 and KDR expression was higher in lung cancer." (PMID 22593690, 2012). "A KDR promoter-driven CD/TK plasmid pcDNA3-KDRp-CDglyTK was constructed and introduced into the lung cancer cell lines with different KDR expressing levels." (PMID 21418659, 2011). "Our work suggests that the KDR promoter is capable of regulating a double suicide gene system in human lung cancer cells, thus providing laboratory evidence to develop a gene therapy approach against various cancers." (PMID 21418659, 2011). "Our results indicate the double suicide genes regulated by the KDR promoter can be specifically expressed in the KDR-expressing cells such as human lung cancer cells." (PMID 21418659, 2011). "As these pathways exhibit compensatory activation upon cabozantinib treatment in resistant cells, we investigated whether VEGFC/KDR/NRP2 knockdown elicited a decrease in FGF/YAP/TAZ/AXL expression in resistant lung cancer cells." (PMID 40843133, 2025). "Next, we examined KDR as a therapeutic target for lung cancer." (PMID 38260532, 2025). "In particular, FLT1 predicted by DriverMP has high sequence similarity to the KDR gene associated with lung cancer in CGC, and related studies showed that tumors expressing both FLT1 and KDR may have a greater malignant potential and a poorer prognosis." (PMID 38091511, 2022). "However, according to the studies that were conducted on A549, TTAC-0001 was able to show antitumor activity in low VEGFR-2/KDR expressing lung cancer xenograft models as well." (PMID 26325365, 2015). "In addition, KDR, a target gene for miR-497 in lung cancer, could boost cancer cell growth and inhibit cell apoptosis." (PMID 36118855, 2022). "In this study, the potential targets of Pinellia ternata highly overlap with lung cancer pathological genes, with FGFR4, CDK2, JAK2, KDR, PAK4, PTK2 and PDGFRA being the core." (PMID 42149884, 2026). "In REMI-LUAD, known lung cancer–specific LR pairs were identified, including GREM1:KDR, which was experimentally validated between fibroblast and malignant cells." (PMID 35302849, 2022). "Conversely, seven of the downregulated hub genes (TLR4, PECAM1, SELP, CXCL12, VWF, KDR, and CD34) showed both low expression and good prognosis in lung cancer patients (p < 0.05)." (PMID 33627711, 2021).
lung cancer (continued). "Despite the high gene expression levels of VEGFA, PGF, FLT1, KDR, MMP-2, TIMP-1, and TIMP-2, only KDR and TIMP-1 were high at the protein level in the lung cancer resections." (PMID 22593690, 2012). "Lung cancer resections had higher expression levels of TIMP-1 compared to pneumothorax and transplant biopsies while the level of KDR was higher in both the lung cancer and transplant biopsies." (PMID 22593690, 2012). "The gene expression level of VEGFA, PGF, and their receptors FLT1 and KDR as well as MMP-2 and the inhibitors TIMP-1 and TIMP-2 was higher in samples from lung cancer resections compared to pneumothorax and transplant biopsy samples." (PMID 22593690, 2012). "Angiogenesis in lung cancer tissues not only depends on the amount of VEGF secretion, but also requires a series of signal transduction events downstream of receptor binding, namely FLT-1 and KDR." (PMID 36870024, 2023). "In order to elucidate the effect of VEGF on A549 and SKMES1 lung cancer cells upon knockdown/blockade of all three VEGF receptors (NP1, NP2, KDR), a combined siRNA (NP1, NP2) and receptor blockade (KDR) approach was used (siCombo) in the presence or absence of VEGF." (PMID 25889301, 2015). "The gene expression level of VEGFA, PGF, and their receptors FLT1 and KDR as well as MMP-2 and the inhibitors TIMP-1 and TIMP-2 was significantly higher in lung cancer specimens compared to pneumothorax samples and biopsies from lung transplant patients (P < 0.001)." (PMID 22593690, 2012). "First, we determined whether troglitazone affects the expression of VEGF-A and its receptors, fms-like tyrosine kinase (FLT-1/VEGFR1), kinase insert domain receptor 1 (KDR/VEGFR2), and neuropilin-1 (NRP-1) in the human lung cancer cell lines, RERF-LC-AI, SK-MES-1, PC-14, and A549." (PMID 20214829, 2010).
diabetes (100 papers, 2010 to 2025). "Diabetes was also shown to be significantly associated with a reduction in the number of CD34 + KDR + and KDR + EPC subtypes." (PMID 39186241, 2024). "Understanding the molecular mechanisms, including genetic factors such as KDR polymorphisms, is important for the pathogenesis of diabetes-related vascular disease." (PMID 39273385, 2024). "The major findings in this study were that preconception diabetes is associated with failure to respond to pregnancy-driven elevations in CPCs (CD34+CD45dimSSlow cells) and CACs (CD133+KDR+ and CD133+KDR- cells)." (PMID 28278173, 2017). "3-Kinase-Akt pathway (PI3K) is an important VEGF signaling pathway mediated by KDR, and the altered pAkt/Akt ratio observed in diabetic skin could finally result in a reduced PECAM-positive capillary net as observed in db/db PrU." (PMID 35386010, 2022). "Participants with diabetes had significantly supressed EPC numbers (CD45-CD34 + CD133 + KDR+) and CD34 + KDR + and KDR + EPC subtypes." (PMID 39186241, 2024). "After RT-qPCR analysis, it was found that the mRNA expression of VEGFA, KDR, MAPK14, and PPARA showed significant differences between normal and diabetes mellitus mice, with a retracement after FBT treatment." (PMID 38304230, 2023). "Here we addressed the dual impacts of diabetes and pregnancy on CPCs (CD34+CD45dimSSlow), CACs (CD34+CD45dimSSlow expressing CD133 and/or KDR) and on early outgrowth colonies." (PMID 28278173, 2017). "Regarding the subpopulation of CD45dimCD34+KDR+ cells also expressing the homing marker CXCR4+, all diabetes treatment categories presented significantly decreased circulating levels by comparison with nondiabetic patients." (PMID 24934236, 2014). "Interestingly, although the level of chemokine SDF-1 was shown to be almost ~ 3-fold higher in participants with diabetes, as reported in the literature, the number of CD34 + CD133 + KDR + and KDR + cells were substantially suppressed." (PMID 39186241, 2024). "The VEGF receptors FLT1 and KDR significantly decreased after 12 weeks in the control and diabetic rats (p<0.02), which is most likely due to age effects, not diabetes." (PMID 23878504, 2013). "To assess whether the differentiation potential of outgrowth CACs towards an EC phenotype was altered in diabetes and MVD we determined the percentage of CACs positive for KDR or eNOS staining using TissueFAXS analysis." (PMID 22648662, 2012). "In contrast to the total CD34+ cell population, in non-diabetic patients with MVD (PAD or CAD), the CD34+KDR+ progenitor cell subset was reduced to the same extent (1.7-fold reduction) as observed in diabetes when compared with healthy controls (p < 0.05)." (PMID 22648662, 2012). "From the negative binomial regression results, diabetes was the only health condition to affect EPC numbers (cells which were negative for CD45 and positive for CD34, CD133 and KDR)." (PMID 39186241, 2024). "Expression of KDR (Flk-1, VEGFR-2), the major receptor mediating the proangiogenic VEGF action, was higher in db/db cells, and not modified by rosiglitazone, while Flt-1 (VEGFR-1) level was affected neither by diabetes nor by rosiglitazone." (PMID 25361524, 2014). "Diabetes did not alter the mRNA expression of the VEGF receptors FLT1 and KDR." (PMID 23878504, 2013). "Using established FACS protocols for the detection of EPCs and SMPCs we observed that the frequency of circulating CD34+ and CD34+KDR+ cells is reduced in patients with diabetes, whereas the levels of CD14+CD105+ SMPCs are not significantly changed by the presence of diabetes." (PMID 22648662, 2012).
colon carcinoma (97 papers, 2003 to 2025). "The expression of VEGF and its receptor, KDR, has been correlated with vascularity, metastasis, and proliferation in human colon cancer." (PMID 38612588, 2024). "The specific activity of the KDR promoter to deliver both TK and CD genes (KDR/CD-TK) in colon cancer cells has been studied." (PMID 26648599, 2015). "This study aimed to extend the previous study of brucine and to evaluate its inhibition on colon cancer cell growth through mediating KDR and its signalling pathway of phosphorylation." (PMID 23905676, 2013). "So the KDR and main pathway molecules, PKCα, PLCγ, Raf1, PKCβ and mTOR, were selected for the mechanism research of suppressing colon cancer cell growth by brucine." (PMID 23905676, 2013). "Strikingly our results on the role of activated MR in the attenuation of the expression of KDR in MR-transfected colon cancer cells, agree with similar data obtained in endothelial progenitor cells and HUVEC." (PMID 23555666, 2013). "Human VEGFR expression profile varied widely depending on tumor types with particularly high levels of human FLT1/VEGFR1 transcripts in colon cancers and non small cell lung carcinomas, and upper levels of human KDR/VEGFR2 transcripts in non small cell lung carcinomas." (PMID 24625025, 2014). "In addition, brucine could suppress colon cancer via the regulation of Wnt/β-catenin and KDR signaling pathways 11,12." (PMID 37779869, 2023). "(i) In total, 105 plants (33 edible) were found to interact with 4 target proteins (TEK, KDR, FGR1 and TOP1) of the FDA approved colon cancer drugs and 43 of their first-degree neighbors." (PMID 24886433, 2014). "Using an in vitro model based on a colon carcinoma cell line, in which we forced MR expression, we also provide the evidence that activated MR can attenuate the expression of VEGFA and its receptor 2/KDR." (PMID 23555666, 2013).
non-small cell lung carcinoma (89 papers, 2009 to 2026). A group of at least three distinct histological types of lung cancer, including non-small cell squamous cell carcinoma, adenocarcinoma, and large cell carcinoma. "On the other hand, the mutation status of MUC6 and three other genes (ATR, ERBB3 and KDR) was obtained as a marker for the recurrence of non-small-cell lung cancer (NSCLC) patients." (PMID 37504272, 2023). "Moreover, Q472H mutation was found to increase KDR protein phosphorylation and associated with MVD in non-small cell lung cancer." (PMID 27077911, 2016). "Bioinformatic analyses have demonstrated that EGFR, KDR, FN1, TGFB1 as well as PCNA are interacting with VEGF-A and are involved in non-small cell lung cancer tumorigenesis." (PMID 35252204, 2022). "Copy number gain was also noted in KDR (VEGFR-2), a mediator of angiogenesis and its expression correlated with poor outcome in non-small cell lung carcinoma." (PMID 24943349, 2014).
pancreatic cancer (88 papers, 2004 to 2025). "have analyzed KDR rs2071559 polymorphism association with pancreatic cancer." (PMID 37803932, 2023). "Carriers of the 604G variant allele (single genotypes, combined genotypes) were more frequent among acute pancreatitis and pancreatic cancer than among controls, suggesting that the KDR 604G allele may confer an increased risk for these diseases." (PMID 28218664, 2017). "KDR 604AG and AG + GG genotypes were more prevalent in acute pancreatitis and pancreatic cancer patients than in controls." (PMID 28218664, 2017). "In our study we aimed to investigate the involvement of VEGFR-2/KDR gene polymorphism (604A>G, rs2071559) in pancreatic pathology, in inflammation and neo-angiogenesis in pancreatic tumor." (PMID 28218664, 2017). "It is highly cytotoxic to tumor endothelial cells overexpressing VEGF receptor-2 (VEGFR-2/KDR/Flk1) and inhibits the growth of primary tumors in subcutaneous models of breast and prostate cancer and inhibits metastatic dissemination in orthotopic models of pancreatic cancer." (PMID 22069683, 2010).
prostate carcinoma (86 papers, 2006 to 2025). A carcinoma that arises from epithelial cells of the prostate gland. "Based on the role of hypoxia-associated molecules in cancer cell biological behaviour and clinical outcome, we assumed there might be an association, at the genetic and protein level, between HIF1A, LOX, CA9 and KDR genetic variants, the protein expression and prostate carcinoma." (PMID 28143503, 2017). "In the study of prostate cancer and this gene, it was found that KDR has a specific promoting effect on the proliferation of prostate cancer." (PMID 39771106, 2024). "Specifically, miR-221 is reported to regulate KDR (Kinase Insert Domain Receptor)—also known as VEGFR2 (Vascular Endothelial Growth Factor Receptor 2)—in ccRCC and prostate cancer, thereby regulating the sensitivity towards sunitinib." (PMID 37046643, 2023). "The KDR gene recognizes vascular endothelial growth factor receptor-2, and the KDR Gln472His mutation has been detected in lung and prostate cancers." (PMID 32113465, 2020). "The genotypic distributions for the putative functional target SNPs in HIF1A, LOX, CA9 and KDR were similar between nodular prostate hyperplasia and prostate carcinomas." (PMID 28143503, 2017). "Likewise, high-grade prostate carcinomas showed much less KDR expression than low or moderate grade tumors." (PMID 16780590, 2006). "In this study we observed that the inherited genetic variants in LOX and KDR seem to modulate the expression of LOX and VEGFR2 in carcinoma cells, supporting a gene-tumor microenvironment interaction in the activation of hypoxia-driven pathways in prostate carcinoma." (PMID 28143503, 2017). "Of note, prostate cancer metastases from the Dream Team cohort also displayed relatively high correlation coefficients of FAP with FLT1 and KDR—thereby potentially mirroring the importance of angiogenesis in high-risk prostate cancer, as previously reported." (PMID 36672341, 2023). "Compound 4b only inhibited seven other kinases (Aurora A, KDR/VEGFR2, SGK1, FLT4/VEGFR3, PIM1, PKD2, and LCK), to similar extent as CK2, and turned out to be cell-permeable and capable of inducing apoptosis in the prostate cancer cell LNCaP." (PMID 29462988, 2018). "Results presented here warrant further research in larger samples in order to evaluate the predictive and prognostic value of KDR and LOX SNPs in prostate carcinoma." (PMID 28143503, 2017). "In agreement with our results, Flt-1 and KDR (both receptors for VEGF) have been identified on malignant cells from human CNS, breast, prostate cancer and in cell lines derived from these tumors." (PMID 17877803, 2007). "Additional cell lines, including a human prostate cancer cell line (PC-3), immortalized mouse aortic endothelial cells (iMAEC) and monkey kidney fibroblast (COS-7) cells were transfected with Cy3-labeled VEGF, KDR and GAPDH siRNAs by SW treatment." (PMID 26243452, 2015). "Therefore, despite functional SNPs in genes of pathways downstream of HIF-1α, such as KDR, LOX and CAIX, have not been studied so far in prostate carcinoma patients, they merit further research as they represent key molecules in hypoxia-generated stimulus in cancer." (PMID 28143503, 2017).
osteosarcoma (65 papers, 2015 to 2026). A usually aggressive malignant bone-forming mesenchymal neoplasm, predominantly affecting adolescents and young adults. "The aim of this study was to evaluate the prognostic value of germline polymorphisms in key genes of the VEGF signaling pathway (VEGFA, FLT1 and KDR) in a prospective multicenter cohort of patients with localized high-grade osteosarcoma treated with the GEIS-33 protocol." (PMID 41471344, 2025). "Clinical data from our TP53P153Δ osteosarcoma patient revealed KDR amplification." (PMID 37266578, 2023).